FAM74A3 (family with sequence similarity 74 member A3)
Synonyms: OTTHUMG00000067149
Gene: Transcribed processed pseudogene on chromosome 9 (66,976,520 to 66,976,991, reverse strand). Ensembl gene ENSG00000274355.
Diseases named in the same sentence as FAM74A3 in open-access papers:
FAM74A3 is named in the same sentence as 1 disease in open-access papers, as found by Europe PMC text mining. Sharing a sentence is not in itself a finding about the gene and the disease.
FAM74A3 shares sentences with these, for which no sentence is quoted: breast carcinoma (1 paper).